CDH13 (cadherin 13)
Diseases named in the same sentence as CDH13 in open-access papers (continued):
Sharing a sentence is not in itself a finding about the gene and the disease.
ovarian carcinoma (13 papers, 2006 to 2025). A malignant neoplasm originating from the surface ovarian epithelium. "A group of miRNAs (miR-181d, miR-30a-3p, miR-30c, miR-30d, miR-30e-3p, miR-370, miR-493-5p, and miR-532-5p) has been associated with ovarian carcinoma progression and predicted to target CDH13." (PMID 40649905, 2025). "We previously identified that methylation of three genes (MINT31, RASSF1, and CDH13) was significantly associated with Her2/neu overexpression in ovarian carcinoma from the United States." (PMID 22925189, 2012). "CDH13 (H-cadherin) is a cell adherence protein and the loss of CDH13 expression in malignant ovarian tumors has been reported previously." (PMID 23226780, 2012). "CDH13, glutathione S-transferase-π1 (GSTP1) and RASSF1 are frequently methylated in sporadic and BRCA1-associated ovarian cancers." (PMID 24179489, 2013). "In the Module 76, miR-214, known to be involved in cell cycle, has been reported to be dys-regulated in ovarian cancer, and CDH13 is a potential epigenetic biomarker for ovarian cancer." (PMID 22863767, 2012). "We previously identified methylation of three ovarian carcinoma-specific genes (MINT31, RASSF1, and CDH13) significantly associated with Her-2/neu overexpression." (PMID 22925189, 2012). "According to these studies, CDH13 has been found to be methylated in 13–67% of ovarian cancer tissue samples." (PMID 23226780, 2012). "Overall, these data indicated the CDH13 downregulation across ovarian carcinoma subtypes." (PMID 40649905, 2025). "Our results support the role of the CDH13 gene in ovarian cancer." (PMID 23226780, 2012). "In ovarian cancer, aberrant methylation of CpG islands in tumor suppressor genes, including CDKN2B, BRCA1, APC, RASSF1, and CDH13, is a frequent event compared to that in the normal ovarian surface epithelium." (PMID 31615043, 2019). "CDH13, CRABP1, HOXA9, and SCGB3A1 were subjected to direct bisulphite sequencing in the four ovarian carcinoma cell lines." (PMID 17623056, 2007). "APC, CDH13, CRABP1, HOXA9, HOXB5, RASSF1A, and SCGB3A1 were found to be hypermethylated both in the primary tumours and in ovarian cancer cell lines, whereas ADAMTS1 and MGMT were hypermethylated only among cell lines." (PMID 17623056, 2007). "Methylation of hMLH1, analyzed in 138 plasma samples predicted poor survival (hazard ratio: 1.99) while CDH1, CDH13, and APC (out of a 15 gene panel) analyzed in peritoneal fluid from 57 ovarian cancer patients could predict overall survival." (PMID 31608277, 2019). "The investigated gene promoters were chosen from loci previously reported to be methylated in ovarian cancer (n = 7; APC, CDH13, MGMT, MLH1, p14ARF, p16INK4a, RASSF1A) and from loci methylated in other tumour types (n = 6; ADAMTS1, CRABP1, HOXA9, HOXB5, NR3C1, SCGB3A1)." (PMID 17623056, 2007). "Subsequent RT-qPCR analyses of ovarian carcinoma tissues revealed that in Her2/neu-negative tumors, CDH13 was silenced through miRNA-mediated mechanisms, whereas in Her2/neu-positive tumors, these miRNAs were suppressed and CDH13 was repressed via promoter methylation." (PMID 40649905, 2025). "The methylation frequencies of RASSFIA, CDH13, CACNA1A, HIN-1, DKN2B, sFRP5, ID4, and ESR were significantly higher in the clear-cell type of ovarian carcinoma than in the non-clear-cell type." (PMID 22871047, 2012). "Moreover, the methylation frequencies of RASSFIA, CDH13, CACNA1A, HIN-1, DKN2B, sFRP5, ID4, and ESR were significantly higher among OCCA than those in non-clear-cell types of ovarian carcinoma." (PMID 22871047, 2012).
colorectal cancer (12 papers, 2004 to 2026). A primary or metastatic malignant neoplasm that affects the colon or rectum. "CDH13, encoding another cadherin protein H-cadherin, has also been reported to be methylated in colorectal cancer, an established complication of longstanding ulcerative colitis." (PMID 25303049, 2014). "Moreover, CDH13, encoding another cadherin protein H-cadherin has been shown to be methylated in colorectal cancer, an established complication of longstanding ulcerative colitis." (PMID 25303049, 2014). "An analysis of TCGA data via the ENCORI platform further revealed an inverse correlation between miR-377 and CDH13 expression in colorectal cancer samples." (PMID 40649905, 2025). "In this study, we investigated the methylation status of CDH13 gene and detected aberrant promoter methylation in 27 of 84 (32%) colorectal cancers." (PMID 14997203, 2004). "According to the previous study, 49% of colorectal cancers that were collected from American colorectal cancer patients showed CDH13 methylation." (PMID 14997203, 2004). "In this study, we investigated the methylation status of CDH13 in 84 colorectal cancers that were examined pathologically." (PMID 14997203, 2004). "To determine the role of CDH13 inactivation in colorectal cancer, we examined the correlation of methylation status with the clinicopathological features." (PMID 14997203, 2004). "In this study, we investigated the methylation status of CDH13 in colorectal cancers and found that almost all (83%) poorly differentiated colorectal cancers presented CDH13 methylation, while only 28% of other differentiated colorectal cancers did." (PMID 14997203, 2004). "It has recently become clear that CDH13 (H-cadherin, T-cadherin) expression is frequently silenced by aberrant methylation in colorectal cancers and adenomas." (PMID 14997203, 2004). "Ubiquitous methylation of CDH13 in colorectal cancers indicated that it occurs at an early stage in the multistage process of oncogenesis." (PMID 15292927, 2004). "We first examined the methylation status of CDH13 in colorectal cancer cell lines (SW1083, SW1116, and SW1417) and an oesophageal squamous cell cancer cell line (TE1) using MSP." (PMID 14997203, 2004). "We found a significant difference in histology (P=0.0053) when we compared the CDH13 methylation of poorly differentiated colorectal cancers to that of differentiated ones." (PMID 14997203, 2004). "Ubiquitous methylation of CDH13 in colorectal cancers and adenomas indicated that such methylation occurs at an early stage in the multistage process of oncogenesis." (PMID 14997203, 2004). "Interestingly, CDH13 was identified as a direct target of miR-377-3p in both colorectal cancer and an Alzheimer’s disease model, resulting in its downregulated expression." (PMID 40649905, 2025). "Aberrant promoter methylation of the CDH13 gene was detected in 27 of 84 (32%) colorectal cancers." (PMID 14997203, 2004). "Therefore, it is conceivable that CDH13 is inactivated in colorectal cancers by promoter methylation, leading to cancer cell dissociation, which is a characteristic of poorly differentiated carcinoma." (PMID 14997203, 2004). "For instance, p16 demonstrates hypermethylation in colorectal cancer, leukemia, and gastric cancer, as well as CDH1, APC, and CDH13 in leukemia." (PMID 39246954, 2024). "As described, the methylation of CDH13 gene would not be complete, suggesting that the CDH13 gene expression has not been inhibited completely in primary colorectal cancers." (PMID 14997203, 2004). "All colorectal cancer cell lines that demonstrated methylation of the CDH13 promoter lacked CDH13 gene expression, while CDH13 was expressed in the oesophageal cancer cell line with unmethylation of the CDH13." (PMID 14997203, 2004). "In our previous study, CDH13 methylation was detected in 27 of 84 primary colorectal cancers (32%) (data not shown)." (PMID 15292927, 2004).
colorectal cancer (continued). "However, we do not yet know what roles CDH13 methylation play in colorectal cancers." (PMID 14997203, 2004).
Obesity (12 papers, 2015 to 2026). Accumulation of substantial excess body fat. "Several studies have shown the association of CDH13 variants with obesity or the syndrome of obesity." (PMID 26600672, 2015). "Follow-up studies need to confirm the observed interaction with CDH13 SNPs and must assess whether the finding is related to recent evidence on the modifying effect of obesity on the association between PM10 and decline in lung function." (PMID 25127211, 2015). "Previous studies have shown gene-gene (epistatic effect) and gene-gender interactions between CDH13 genotypes and metabolic syndrome and between CDH13 genotypes and obesity, respectively." (PMID 26600672, 2015). "Recent advances have highlighted that adiponectin, a well‐characterized insulin‐sensitizing adipokine, and its receptors, especially T‐cadherin (also known as H‐cadherin or CDH13), may resist obesity‐related carcinogenesis." (PMID 37220892, 2023). "Studying obesity with and without OSA, changes (unadjusted for multiple comparisons) in some peptides belonging to CDH13, FGB, COL1A1, and COL3A1 were also identified." (PMID 39858454, 2025).
depression (11 papers, 2012 to 2025). "Both genes have been linked to depression, but a polymorphism of the CDH13 gene has also been associated with an increased risk of migraine." (PMID 40157903, 2025). "In particular, among the four causal genes with sb-pQTLs we found for depression, cadherin 13 (CDH13) regulates GABAergic neurons, axon guidance and synaptic formation." (PMID 37653343, 2023). "In addition, CDH13 has also been implicated by GWAS in depression (rs10514585), extraversion (rs4783307, rs8056579), agreeableness (rs9940706) and response to antipsychotic therapy (rs17216786), as well as in a meta-analysis for extraversion (rs8057458)." (PMID 22952603, 2012). "Copy number and common variants in Cadherin-13 (CDH13, also known as T-Cadherin) have been associated with ASD, ADHD, and comorbid disorders such as depression and alcohol dependence." (PMID 33972691, 2022). "This is of great importance given that mutations in Cdh13 have been associated with a vast number of neuropsychiatric disorders including ADHD, depression, schizophrenia, and bipolar disorder." (PMID 33949949, 2021). "As Cdh8, Cdh13, and Dcc/Netrin-1 have been linked to ASD, depression, and schizophrenia, investigating their role in wiring the healthy brain can provide important clues about how mPFC circuitry is perturbed in disease." (PMID 33949949, 2021). "Its recurring association with several other neuropsychiatric disorders, such as autism spectrum disorders (ASD), major depression, bipolar disorder, and substance dependence, points to a broad involvement of CDH13 in neurodevelopmental processes." (PMID 34573337, 2021). "The cell—cell signaling gene CDH13 is associated with a wide spectrum of neuropsychiatric disorders, including attention-deficit/hyperactivity disorder (ADHD), autism, and major depression." (PMID 34573337, 2021). "Interestingly, we also observed that 28 genes actively expressed at this stage, including genes such as NFIA, CDH13, TCF4, and DLG2, were associated with intellectual disabilities, autism spectrum disorders, irritability, and depression." (PMID 39452151, 2024). "Moreover, CDH13 was found to be upregulated in the amygdala of depression patients and, in parallel, was shown to play a protective role in various models exposed to environmental stressors." (PMID 36011346, 2022). "Cadherin-13 (CDH13) is implicated in multiple neurodevelopmental disorders, such as autism spectrum disorders, attention-deficit/hyperactivity disorder (ADHD), major depressive disorder, and substance use disorders." (PMID 33560471, 2021).
hepatocellular carcinoma (10 papers, 2014 to 2025). A malignant tumor that arises from hepatocytes. "The overexpression of CDH13 and AKAP13A, both of which were found to be truncated in our study, have been reported to correlate with a higher risk of late recurrence of hepatocellular carcinoma." (PMID 24405831, 2014). "CDH13 was notably a top upregulated gene obtained from the linear modeling of hepatocellular carcinoma (only after GABRD and PLVAP) in an earlier analysis; these observations point to a consistent role for members of the cadherin gene family in cancer progression in gastrointestinal cancers." (PMID 39484215, 2024). "In hepatocellular carcinoma, miR-665 can promote cancer cell metastasis, enhance anti-apoptotic ability, and increase the drug resistance of hepatocellular carcinoma cells to sorafenib by inhibiting CDH13." (PMID 37894282, 2023). "Furthermore, Cdh13 suppresses activation of c-Jun/JNK and induces G2/M cell cycle arrest in hepatocellular carcinoma cells." (PMID 26420260, 2015).
breast tumor (9 papers, 2007 to 2022). "Our most notable observation is the presence of a significantly higher methylation at a CpG site in the CDH13 gene in breast tumor samples from AA women when compared with EA women among young and ER-negative patients." (PMID 22701537, 2012). "Bisulfite pyrosequencing is used to screen 6 putative tumor suppressor genes (HIN-1, RASSF1A, RIL, CDH13, RARβ2 and E-cadherin) in 38 pairs of primary breast tumors and lymph node metastases." (PMID 20642860, 2010). "We used bisulfite pyrosequencing to screen 6 putative tumor suppressor genes (HIN-1, RASSF1A, RIL, CDH13, RARβ2 and E-cadherin) in 38 pairs of primary breast tumors and lymph node metastases." (PMID 20642860, 2010). "Our results suggested that methylation reflected by the RIL/CDH13 panel might have a role in the phenotype of basal-like breast tumors." (PMID 17764565, 2007). "The promoter analysis of IL1B, CDH13, and PTPN11, using SMART App, showed methylation status in breast tumor patient samples." (PMID 36474139, 2022). "Our data suggests that DNA methylation reflected by the CDH13, RASSF1A and SFRP1 locus panel might have a role in the phenotype of breast tumor subtypes." (PMID 22701537, 2012). "Five of the genes, all known tumor suppressor genes (RASSF1A, RARβ2, CDH13, HIN1 and SFRP1), were found to be frequently hypermethylated in breast tumor tissues but not in the adjacent non-cancerous tissues." (PMID 22701537, 2012).
endothelial dysfunction (9 papers, 2014 to 2025). In vascular diseases, endothelial dysfunction is a systemic pathological state of the endothelium (the inner lining of blood vessels) and can be broadly defined as an imbalance between vasodilating and vasoconstricting substances produced by (or acting on) the endothelium. "Therefore, in comparison to the controls, Cdh13−/− mice exhibited only mild signs of vascular damage due to angiotensin II-induced endothelial dysfunction." (PMID 40109358, 2025).
gastric cancer (9 papers, 2004 to 2025). A primary or metastatic malignant neoplasm involving the stomach. "miR-495-3p emerged from this pipeline as a putative regulator of several cadherins, including CDH13, but its own expression is reduced in gastric cancer." (PMID 40649905, 2025). "Inhibition of H19 has been shown to repress MMP9, vimentin, E-cadherin, and CDH13 expression in retinoblastoma, colorectal, and gastric cancers, thereby contributing to epithelial to mesenchymal transition progression." (PMID 40649905, 2025). "As a control, we screened for CDH13 methylation in the corresponding normal epithelial DNA of 37 oesophageal and 66 gastric cancer patients." (PMID 15292927, 2004). "Our results suggested that the aberrant methylation of CDH13 gene has been shown frequently in oesophageal and gastric cancers." (PMID 15292927, 2004). "In this study, CDH13 gene was methylated frequently in gastric cancers, suggesting that the inactivation of this gene plays an important role in this cancer while it does not do so in oesophageal squamous cell cancers." (PMID 15292927, 2004). "Five of 37 oesophageal cancers (14%) and 23 of 66 gastric cancers (35%) demonstrated abnormal methylation of the CDH13 promoter." (PMID 15292927, 2004). "Therefore, it is conceivable that CDH13 was also inactivated in gastric cancers by promoter methylation." (PMID 15292927, 2004). "We examined CDH13 methylation in oesophageal and gastric carcinomas." (PMID 15292927, 2004). "We then examined CDH13 methylation in oesophageal and gastric carcinomas." (PMID 15292927, 2004). "CDH13 (also known as T-cadherin) at locus 16q23.3 is involved in several neoplasms, besides CRC, prostate- and gastric cancer." (PMID 39543761, 2024). "Three colon and two gastric cancer cell lines that demonstrated only methylation of the CDH13 promoter lacked CDH13 gene expression, while CDH13 was expressed in all other cell lines with unmethylation of the CDH13 promoter including one gastric and three oesophageal cancer cell lines." (PMID 15292927, 2004).
glioma (9 papers, 2010 to 2021). A benign or malignant brain and spinal cord tumor that arises from glial cells (astrocytes, oligodendrocytes, ependymal cells). "In addition, H19 acts as a miRNA precursor gene to promote glioma growth, which induces the production of miRNA-675 that further modulates expression of cancer-associated calmodulin 13 (CDH13)." (PMID 34081618, 2021). "H19 transcript can produce a miRNA (miR-675), which directly regulates CDH13 (Cadherin 13), thereby modulating glioma cell invasion." (PMID 29137410, 2017). "We used Pearson correlations to analyze the relationship between miR-675 and CDH13 in 158 glioma specimens from CGGA date and determined the expression of miR-675 was correlated with CDH13 in glioma (P = 0.0017)." (PMID 24466011, 2014). "In the present study, we firstly showed the role of the H19/miR-675/CDH13 pathway in glioma development." (PMID 24466011, 2014). "Furthermore, our results proved that the effect of miR-675 on invasion in glioma cells by directly targeting CDH13." (PMID 24466011, 2014). "But the effect of CDH13 on glioma is still poorly understood." (PMID 24466011, 2014). "Moreover, as a precursor, H19 derived miR-675 and then regulated Cadherin 13 (CDH13) which is the directly target of miR-675, thereby modulating glioma cell invasion." (PMID 24466011, 2014). "And H19 regulated glioma cell invasion by deriving miR-675 and inhibited CDH13." (PMID 24466011, 2014). "Among these, CDH13, TIAM1 and PCDH17 were up- and FLRT1 and OPCML down-regulated, thus indicating that the invasion capacity of glioma cells can be altered by cisplatin treatment." (PMID 21637621, 2010). "H19-derived miR-675 might regulate glioma-cell proliferation and migration through cyclin dependent kinase 6 (CDK6) and Cadherin 13 (CDH13), and predict poor prognosis for patients with glioma." (PMID 32650527, 2020).
autism (8 papers, 2013 to 2022). Persistent deficits in social interaction and communication and interaction as well as a markedly restricted repertoire of activity and interest as well as repetitive patterns of behavior. "Cadherin-13 (CDH13) has been associated with autism and attention-deficit/hyperactivity disorder." (PMID 33972691, 2022). "In addition, deletions in CDH13 were associated with autism, suggesting a role of CHD13 in the development of psychological disorders." (PMID 33384710, 2020). "A genome-wide recurrent de novo analysis also includes the CDH13 gene in rare copy-number variations in autism families." (PMID 24756565, 2014). "A scan for the IQ discrepancy in autism revealed a unique truncated cadherin, cadherin 13 (CDH13), which has also been suggested as a candidate for autism." (PMID 24756565, 2014). "Notably, these included transcripts for adhesion proteins such as CDH13, CDH9, CDH15 and SLITRKs, all strongly linked to ASD, presynaptic molecules such as SYNIII and SV2C, associated with non-syndromic autism and SCZ, and post-synaptic transcripts such as DLGAP2 and GRIN2D, linked to SCZ." (PMID 30185603, 2018). "Taken together, our results indicate that CDH13 is a negative regulator of inhibitory synapses in the hippocampus, and provide insights into how CDH13 dysfunction may contribute to the excitatory/inhibitory imbalance observed in neurodevelopmental disorders, such as ADHD and autism." (PMID 26460479, 2015).